ALDH1A1 (aldehyde dehydrogenase 1 family member A1)
Diseases named in the same sentence as ALDH1A1 in open-access papers (continued):
Sharing a sentence is not in itself a finding about the gene and the disease.
melanoma (continued). "Confocal microscopy analyses of matrigel-coated culture transwells showed that sh-AhR + sh-Aldh1a1 cells had a significant impairment to invade as compared to sh-AhR melanoma cells." (PMID 26242870, 2015). "Furthermore, Notch1 enhances the proangiogenic properties of melanoma cells that overexpress ALDH1A1, thereby facilitating tumor vascularization and progression." (PMID 40399946, 2025). "In melanoma, ALDH1A1 mediates resistance to MAPK/ERK inhibitors by activating PI3K/AKT signaling." (PMID 40868269, 2025). "Similarly, ALDH1A1 overexpression in melanoma cells was found to correlate with an upregulated secretion of proangiogenic factors promoting angiogenic traits in surrounding endothelial cells through the activation of the intracellular Notch signaling cascade." (PMID 39199632, 2024). "ALDH1A1 regulates either RA-driven target genes connected to aggressiveness/stem cell activities or genes with RA response elements (RAREs) in CSCs from human melanoma, making this isozyme a potential therapeutic target in melanoma." (PMID 37359050, 2023). "However, ALDH1A3 mRNA expression was more than 200 times higher than ALDH1A1 in ALDEFLUOR+ subpopulations isolated from melanoma cell lines." (PMID 37686694, 2023). "ALDEFLUOR-positive melanoma CSCs were associated with chemoresistance, and ALDH1A (ALDH1A1 and ALDH1A3) silencing could attenuate cell proliferation and induce apoptosis in ALDEFLUOR-positive melanoma CSCs in vitro and suppress melanoma tumorigenesis in vivo." (PMID 36651035, 2023). "constructed a mutational subtype of melanoma based on the BRAF mutation patterns of 2 FAM-related genes, ALDH1A1 and ALDH1A3; however, this CM subtype accounts for ALDH1A3 expression as only a prognostic marker for BRAF/MEK inhibitor treatment response in BRAF-mutant metastatic melanoma patients." (PMID 36466837, 2022). "ALDH1A1 overexpression was also found to occur in skin cancers, particularly in melanomas." (PMID 35814382, 2022). "In this context, AhR may antagonize the pro-tumoral effects of Aldh1a1; thus, an AhRlow/Aldh1a1high phenotype could be indicative of a poor outcome in melanoma." (PMID 33451095, 2021). "However, in CSCs from human melanoma, ALDH1A1 modulates either RA-driven target genes with RAREs and genes associated with aggressiveness/stem cell functions, making this isozyme a putative therapeutic target in melanoma." (PMID 30541574, 2018). "Indeed, Aldh1a1 downmodulation markedly reduced the number of cancer stem-like cells and impaired primary tumorigenesis and lung metastasis in AhR depleted melanoma cells." (PMID 26242870, 2015). "We suggest that the coordinated expression of AhR and Aldh1a1 could be a useful molecular marker in melanoma." (PMID 26242870, 2015). "We next addressed whether Aldh1a1 was required to maintain the population of stem-like cells in our melanoma cell cultures." (PMID 26242870, 2015). "Moreover, Sox2 failed to rescue the migration of Aldh1a1-depleted sh-AhR + sh-Aldh1a1 cells, further supporting a functional interaction between Aldh1a1 and Sox2 in murine melanoma cells." (PMID 26242870, 2015). "We therefore suggest that AhR may block melanoma by inhibiting the pro-tumoral effects of Aldh1a1, and that coordinated expression of AhR and Aldh1a1 could be a useful molecular marker in melanoma." (PMID 26242870, 2015). "Since AhR expression appears to be reduced in advanced human melanomas, it will be interesting to investigate whether Aldh1a1 becomes upregulated in the same tumors and if it contributes to disease progression." (PMID 26242870, 2015). "In particular, ALDHs may be involved in cancer stemness in melanomas, and ALDH1A1 has been identified as one of the key ALDH isozymes involved in this process." (PMID 26029997, 2015). "We then hypothesized that the increased tumorigenic and metastatic potential of sh-AhR melanoma cells could depend, at least in part, to their high Aldh1a1 activity." (PMID 26242870, 2015).
melanoma (continued). "The functional interaction between Aldh1a1 and AhR could be also relevant for the control of migration and invasion of melanoma cells." (PMID 26242870, 2015). "Although our results strongly support that AhR modulates Aldh1a1 mRNA expression in murine melanoma cells, it is still undefined whether it requires AhR binding to the XRE elements present in the Aldh1a1 promoter." (PMID 26242870, 2015). "In this work, we have investigated the Aldh1a1 enzyme as a molecular intermediate whose upregulation in AhR depleted cells could promote melanoma progression." (PMID 26242870, 2015). "Nevertheless, the molecular mechanisms by which Aldh1a1 influences melanoma progression are mostly unknown." (PMID 26242870, 2015). "The main findings from this study are that AhR expression restrains Aldh1a1 activity in murine melanoma cells and that, as a consequence, AhR depletion results in Aldh1a1 upregulation and in the exacerbation of melanoma primary tumorigenesis and metastasis in vivo." (PMID 26242870, 2015). "Since AhR negatively modulate Aldh1a1 activity, melanoma tumors could restrict AhR expression in order to maintain the tumor promoting activity of Aldh1a1." (PMID 26242870, 2015). "However, wound-healing assays revealed that Aldh1a1 interference reduced the migration ability of B16F10 melanoma cells." (PMID 26242870, 2015). "Since AhR may antagonize the protumoral effects of Aldh1a1, the AhRlow-Aldh1a1high phenotype could be indicative of bad outcome in melanoma." (PMID 26242870, 2015). "Moreover, an allogeneic, whole-cell, genetically modified therapeutic melanoma vaccine could generate immune responses to ALDH1A1 and improve long-term survival in advanced melanoma patients." (PMID 35814382, 2022). "Therefore, the functional interaction between AhR and Aldh1a1 could be of potential interest for melanoma progression and therapy." (PMID 26242870, 2015). "Therefore, the tumor suppresor role of AhR in melanoma could take place by antagonizing the Aldh1a1 activity." (PMID 26242870, 2015). "Thus, AhR and Aldh1a1 had opposite expression patterns in both murine and human melanoma cells." (PMID 26242870, 2015). "The evidences showing that Sox2 expression was coincident with Aldh1a1 overactivation, and that Sox2 expression inhibited Aldh1a1 in AhR knockdown cells, suggest the existence of a coordinated pathway involving AhR-Aldh1a1-Sox2 in the regulation of stemness in melanoma cells." (PMID 26242870, 2015). "Pharmacological inhibition of ALDH1A1 also leads to reduced activation of the AKT pathway and can partly restore the effectiveness of BRAFi/MEKi in treating melanoma cells." (PMID 39582535, 2024). "Human ALDH1A family comprises ALDH1A1, strongly expressed in xenografted melanoma, ALDH1A2, and ALDH1A3, strongly expressed in 1205L and A375 human melanoma cell lines and weakly expressed in xenografted melanoma." (PMID 35334544, 2022). "SCD1 inhibition reduced expression of ALDH1A1, Nanog, and Oct4 in NSCLC and reverted chemo-resistance of BRAFpos melanoma cells." (PMID 34727953, 2021). "Recently, we demonstrated that AGI-101H induces ALDH1A1-specific, functional cytotoxic T cells, and stimulates anti-ALDH1 antibody production, which strongly suggests its immune-mediated targeting of melanoma stem-like cells (MSCs)." (PMID 32224883, 2020). "From this, we identified a panel of 6 genes, ALDH1A1, HSP90AB1, KIT, KRT16, SPRR3 and TMEM45B whose expression values discriminated metastatic from primary melanoma (87% classification accuracy)." (PMID 29229936, 2017). "As expected, ALDHhigh melanoma cells express significantly higher levels of ALDH1A3, SOX2 and CD271 than ALDHlow cells by real time PCR, western blotting (SOX2/ALDH1A1) and FACS analysis (CD271)." (PMID 28036292, 2017). "Mouse melanoma B16F10 cells were engineered by retroviral transduction to stably downregulate AhR expression, Aldh1a1 expression or both." (PMID 26242870, 2015).
melanoma (continued). "In vivo xenografts of Aldh1a1high human melanoma cells in immunodeficient nude, NGS or NOD/SCID mice produced larger a more aggressive tumors, suggesting that Aldh1a1 activity favoured tumorigenesis." (PMID 26242870, 2015). "A recent study by Speigl and co-authors analyzed putative CSC markers (ALDH1A1, ABCG2, CD44v7/8, CD44v10, CD133, CD271, and Nestin) in melanoma and revealed widespread expression across cell lines, early-passage strains, and patient tissues, suggesting limited specificity for CSCs." (PMID 40867277, 2025). "More recently, Liao and coworkers developed a dual ALDH1A1+ALDH1A3 peptide–dendritic cell vaccine and found that it induces suppression of tumor growth by eliciting a peculiar T cell immunity that specifically targets ALDH+ melanoma cells." (PMID 39199632, 2024). "ALDH1 (ALDH isozyme 1), specifically the isoforms ALDH1A1 and ALDH1A3, have been reported to be highly expressed and even overactivated in melanoma CSCs and to correlate with different biological properties of tumor-initiating cells, such as tumorigenesis and drug resistance." (PMID 39199632, 2024). "Moreover, the paper explores potential druggable targets for melanoma patients, including ERK5, CD73, ALDH1A1, PLA1A, and DMKN, which hold promise in addressing diagnostic hurdles and guiding personalized therapeutic decisions." (PMID 39582535, 2024). "In addition to these markers, melanoma CSCs show high ALDH activity, especially ALDH1A1 and ALDH1A3 isozymes." (PMID 35048028, 2021). "However, a recent study reported that both ALDH1A1 and ALDH1A3 correlated with favorable prognosis in metastatic BRAF wild-type and BRAF-mutant melanoma, respectively." (PMID 35048028, 2021). "ALDH3A1, the ALDH1A subfamily, comprising ALDH1A1, which synthesizes RA from retinaldehyde and, as such, is crucial in regulating RA signaling, has been used as a CSC marker for many solid tumors, including lung and melanoma." (PMID 31817719, 2019). "In our study, in melanoma cells, we found no role for ALDH1A1 in cell survival and clonogenicity, and inhibitors of RA signaling failed to regulate PD-L1 expression in 3A1high cells." (PMID 31817719, 2019). "However, AhR knockdown increased ALDH1A1 activity and enhances B16F10 melanoma growth through maintaining cancer stem-like phenotypes." (PMID 28137308, 2017). "Depletion of aldehyde dehydrogenase 1a1 (Aldh1a1) impairs the pro-tumorigenic and pro-metastatic advantage of melanoma cells lacking AhR expression (sh-AhR)." (PMID 26242870, 2015). "However, immunohistochemistry and real-time quantitative reverse transcription-PCR (qRT-PCR) reveal that both ALDH1A1 and ALDH1A3 may be expressed in some melanomas." (PMID 35334544, 2022). "Some ALDHs, particularly ALDH1A1, ALDH1A3, and ALDH3A1, are widely regarded as markers of stemness in normal tissues (basal skin, bronchial mucosa cells, human cornea, breast, liver), as well as in several solid tumors (non-small-cell lung cancer (NSCLC), melanoma, gastric, breast)." (PMID 31817719, 2019). "The fact that a constitutively active AhR or a bona-fide endogenous ligand could repress Aldh1a1 gives additional support to such pathway and suggests that non-toxic AhR ligands could inhibit the progression of melanomas having high levels of Aldh1a1 activity." (PMID 26242870, 2015). "In this context, the inverse correlation observed between AhR and Aldh1a1 could gain additional interest considering that AhR protein levels were reduced in high grade human melanomas as compared to non-malignant nevi." (PMID 26242870, 2015). "Interestingly, depletion of basal Aldh1a1 levels in AhR-expressing melanoma cells did not significantly affect tumor growth, suggesting that the overactivation of Aldh1a1 is likely a causal factor increasing the tumorigenicity of AhR deficient melanoma cells." (PMID 26242870, 2015).
melanoma (continued). "This apparent correlation between Sox2 and Aldh1a1 was supported by the observation that ectopic Sox2 expression increased Aldh1a1 mRNA levels in sh-AhR but not in Aldh1a1-interfered melanoma cells, indicating that Sox2 could play a role in maintaining Aldh1a1 expression." (PMID 26242870, 2015). "Interestingly, Sox2 increased Aldh1a1 expression in sh-AhR but not in sh-AhR + sh-Aldh1a1 cells, suggesting that Aldh1a1 and Sox2 may be co-regulated in melanoma cells." (PMID 26242870, 2015). "Altogether, the reason for the differences in ALDH1A1 and ALDH1A3 expression between primary melanomas and melanoma cell lines was not clear." (PMID 36651035, 2023).
prostate carcinoma (64 papers, 2011 to 2025). A carcinoma that arises from epithelial cells of the prostate gland. "Prostate cancer progression is associated with increased interaction between ALDH1A1 and the androgen receptor (AR) and RAR." (PMID 38928275, 2024). "Prostate cancer progression is associated with the increasing interplay of ALDH1A1 with androgen receptor (AR) and retinoid receptor (RAR) transcriptional programs." (PMID 38169509, 2024). "On the other hand, the elevated activity of specific ALDH isoforms, particularly ALDH1A1, has been associated with more aggressive forms of prostate cancer, reflected in higher Gleason scores and poorer prognosis." (PMID 39456547, 2024). "Two SNPs were significantly associated with prostate cancer risk [rs1330286 in ALDH1A1: odds ratio (OR) = 0.88, 95% confidence interval (CI) = 0.83‐0.94, p = 2.45 × 10−4; rs4646653 in ALDH1A3: OR = 1.17, 95% CI =1.07‐1.27, p = 4.33 × 10−4]." (PMID 33068330, 2020). "After adjusting for age and smoking status, we identified that the rs1330286 G allele in ALDH1A1 was associated with a decreased risk of prostate cancer, while the rs4646653 C allele in ALDH1A3 was strongly related to an increased risk of prostate cancer." (PMID 33068330, 2020). "In our study, one SNP in the ALDH1A1 intron region, which has an annotated function of changing motifs, is associated with prostate cancer risk." (PMID 33068330, 2020). "High ALDH1A1 activity is associated with poor prognosis in patients with breast and prostate cancer." (PMID 24405526, 2013). "An increase in ALDH1A1 in prostate cancer bone metastases was associated with high PLK3 expression." (PMID 38928275, 2024). "ALDH1A1 gain in prostate cancer bone metastases is associated with high PLK3 expression." (PMID 38169509, 2024). "Notably, ALDH1, particularly ALDH1A1, has been identified as a biomarker for CSCs in prostate cancer and is clinically associated with poor outcomes." (PMID 39796106, 2024). "Evidence suggested that ALDH1A1 was significantly associated with prostate cancer risk and which could be a prostate cancer stem cells-related marker." (PMID 32984354, 2020). "Moreover, the β-catenin/T-cell factor (TCF) transcriptional complex directly regulates ALDH1A1 gene expression and is associated with radioresistance in prostate cancer progenitors." (PMID 30733805, 2019). "In a prostate cancer cell model, it was reported that irradiation caused durable upregulation of cancer stem cell marker proteins, including aldehyde dehydrogenase 1A1 (ALDH1A1) as well as long-term altered histone methylation patterns of H3K4, H3K36, and H3K27 tri-methylation." (PMID 28977985, 2017). "p63 cytoplasmic aberrance is associated with high ALDH1A1 expression, and it was found that cytoplasmic p63 levels were significantly associated with the frequency of proliferating cells and cells undergoing apoptosis in prostate cancers." (PMID 27447616, 2016). "Interestingly, PLA2G7 silencing reduced the expression of aldehyde dehydrogenase 1A1 (ALDH1A1), described as a prostate cancer stem cell marker and associated with poor prostate cancer outcome." (PMID 22202492, 2011). "In a mouse model of prostate cancer, a tomato diet (rich in lycopene) down-regulated the expression of stem cell-related genes, namely aldehyde dehydrogenase 1A1 gene (Aldh1a1)." (PMID 39859345, 2025). "Studies have shown a positive correlation between ALDH1A1 expression in prostate cancer tissue and Recombinant retinoic acid receptor alpha (RARα) and Erythroblastosis-twenty six 1 (Ets1)." (PMID 39055491, 2024). "These transplantable tumors histopathologically resemble the parental tumors, indicating the crucial role of ALDH1A1 in stemness regulation in prostate cancer." (PMID 39796106, 2024). "Aldehyde dehydrogenase 1 family, member A1 (ALDH1A1) is an aldehyde oxidase that can be targeted by silymarin for the treatment of prostate cancer." (PMID 39055491, 2024).